IL22 (interleukin 22)
Diseases named in the same sentence as IL22 in open-access papers (continued):
Sharing a sentence is not in itself a finding about the gene and the disease.
allergic asthma (continued). "There is evidence that IL-22 and IL-17 participate in the pathogenesis of allergic asthma." (PMID 37445595, 2023). "Our findings are in agreement with the majority of clinical studies investigating IL-22 level in patients with allergic rhinitis and/ or allergic asthma and revealed that concentration of IL-22 in serum or plasma was higher in these patients than in healthy subjects." (PMID 33478443, 2021). "This may suggest that IL-22 is involved in the pathogenesis of allergic asthma, and further studies are needed to confirm the precise roles of IL-22." (PMID 34836520, 2021). "Interleukin-22 is one of the lymphoid cell-derived cytokines, and have exclusive functions on non-hematopoietic cells, especially epithelial cells, playing a critical role in the regulation of allergic asthma airway inflammation." (PMID 34836520, 2021). "Additionally, IL-22 levels were found to be increased in the skin of patients with AD, ACD, and allergic asthma and IL-22 has been suggested as a potential biomarker for allergic disease." (PMID 32449871, 2020). "Subsequent studies showed that the difference in β-glucan surface exposure between A. versicolor and C. cladosporioides was key in the distinct allergic airway profile and that dectin-1 suppressed this Th2 type allergic asthma by promoting IL-17A and IL-22 type immune responses." (PMID 29696023, 2018). "IL-22 has been shown to contribute to allergic asthma during the sensitization phase and to promote lung immunopathology during fungal allergy, but it can also inhibit antigen-induced eosinophil airway inflammation through inhibition of IL-25, of IL-10, or during the challenge phase." (PMID 25860963, 2015). "To further understand the role of IL-22 in allergic asthma, we developed inducible transgenic mice that express IL-22 specifically in the airways to investigate the immune modulatory effects of this cytokine and its underlying mechanisms in the context of OVA-induced lung inflammation." (PMID 25254361, 2014). "We has established a regulatory role for IL-17A and IL-22 in allergic asthma." (PMID 23738146, 2013). "However, it can be expected to be unfavorable, because an upregulation of RORγt with elevated IL-17A and IL-22 levels has been proposed to play a role in immune disorders such as severe allergic asthma, psoriatic arthritis and UV-radiation induced promotion of skin cancer." (PMID 35337918, 2022). "Therefore, the effects of IL-22 on allergic asthma airway inflammation still need further study." (PMID 34836520, 2021). "However, the actual role of IL-22 in allergic asthma is still unclear." (PMID 34836520, 2021). "With this feature IL-22 may be considered as an immune modulator in allergic asthma." (PMID 25254361, 2014). "Once activated, for example by IL-33 or IL-22, ILC2 secrete IL-5 and IL-13, contributing to AHR and airway inflammation in OVA-induced allergic asthma." (PMID 40095032, 2025). "In our study, we detected the IL-22 level in lung homogenates and BALF in allergic asthma model mice and control mice." (PMID 34836520, 2021). "To further understand IL-22 in allergic asthma, we generated transgenic mice that express the cytokine specifically in the airway epithelial cells and investigated the immune modulating effects of IL-22 in OVA allergen induced allergic asthma." (PMID 25254361, 2014). "Interestingly, we found negative correlation between serum IL-22 level and IL-22 level in nasal lavage only in patients with allergic rhinitis together with allergic asthma." (PMID 33478443, 2021). "One possible reason is that the role of IL-22 in allergic asthma is not well defined." (PMID 25254361, 2014). "However, IL-22 related therapies for the treatment of allergic asthma have not been initiated." (PMID 25254361, 2014).
gastric cancer (20 papers, 2015 to 2024). A primary or metastatic malignant neoplasm involving the stomach. "IL-22 produced by cancer-associated fibroblasts has been reported to promote gastric cancer cell invasion via STAT3 and ERK signaling." (PMID 36977736, 2023). "IL-22 gene polymorphisms were found to increase the susceptibility of developing gastric cancer in a study that was conducted on Asian population." (PMID 33042126, 2020). "IL-22 facilitated the invasion of gastric cancer cells by cancer-associated fibroblasts through ERK and STAT3 signaling." (PMID 31528235, 2019). "Furthermore, increased level of intratumoral and circulating IL-22 have been found in gastric cancer patients and are associated with cell survival, migration, proliferation, and angiogenesis." (PMID 33426090, 2020). "In this study, while gastric cancer cells were co-cultured with IL-22-expressing cancer-associated fibroblasts (CAFs) from human gastric cancer tissues, the invasive ability of the gastric cancer cells was significantly enhanced through activation of the STAT3 and ERK signaling pathways." (PMID 26160167, 2015). "Furthermore, it has also been shown that increased CD4 T cells producing IL22 in tumor tissues are associated with tumor progression and poor prognosis of patients, which is consistent with our results in advanced (T3, T4 phase) gastric cancer." (PMID 33426088, 2020). "Moreover, increased IL-22 producing T cell numbers in the tumor and the peripheral blood is associated with poor outcome, indicating that IL-22 facilitates progression of gastric cancer." (PMID 29967613, 2018). "Increased expression of pro‐inflammatory cytokines and chemokines such as IL‐17A, IL‐22, and IL‐1 family members IL‐1β is involved in gastric cancer progression." (PMID 37306187, 2023). "The MAPK/ERK pathways have been shown to play a role in controlling gastric cancer cell migration and invasion induced by IL-22, PRL3, NAIF1, and CCDC134." (PMID 37817112, 2023). "CCL5, CCL22, CCL21, CCL2, and CCL15 were correlated with effector memory CD4 T cell in T1/T2 stage gastric cancer, and the number of cells was associated with the expression of IL3, IL17F, IL18, IL22, and IL31." (PMID 33426088, 2020). "Expression of IL-22 has been reported in the H. pylori-infected gastric tissue of humans and gastric cancer patients." (PMID 26867135, 2016). "Recent evidence indicates that IL-22 promotes gastric cancer development via activation of the STAT3 and ERK signaling pathways." (PMID 26160167, 2015). "IL-17 cells may promote tumor progression through IL-17, IL-22, and IL-26 signaling pathways; thus, targeting IL-17 cells and related signaling pathways may serve as a therapeutic strategy for gastric cancer." (PMID 39676857, 2024). "IL-22 enhances pancreatic and gastric cancer invasion and migration." (PMID 31750252, 2019). "Furthermore, IL-22 supports the migration and invasion of gastric cancer cells." (PMID 29967613, 2018). "Therefore, it is necessary to confirm that (i) the role of H. pylori-mediated upregulation of IL-22 in gastric cancer cells, (ii) the activation of STAT3 dependent on H. pylori-mediated IL-22 and/or H. pylori CagA, (iii) the role of CagA in H. pylori-mediated upregulation of IL-22." (PMID 26160167, 2015). "Compared to normal fibroblasts CAFs overexpress TGFβ and other proteins and secrete IL-22 into the tumor microenvironment which promotes cell invasion via STAT3 and ERK pathways in gastric cancer." (PMID 34854061, 2022). "Similar to our results, a gastric cancer study found that neither G-CSF, GM-CSF, TGF-β, M-CSF, IL-1β, IL17A, IL-6, TNFα, IL10, IFNγ and IL22 were able to induce MC degranulation, while only adrenomedullin did." (PMID 32722549, 2020).
Allergy (19 papers, 2012 to 2024). An allergy is an immune response or reaction to substances that are usually not harmful. "Logistic regression analysis indicated that low cord blood IL-22 levels and a family history of allergies were independent risk factors for eczema (p < 0.05)." (PMID 38606371, 2024). "Logistic regression analysis confirmed that family history of allergy and low levels of IL-22 in umbilical cord blood were independent risk factors for infant eczema at 42 days old (p < 0.05)." (PMID 38606371, 2024). "In summary, both low levels of IL-22 and Family history of allergy serve as risk factors for eczema in infants at 42 days old." (PMID 38606371, 2024). "IL-22 is produced primarily by innate lymphocytes and adaptive T cells in response to lung damage caused by infections, allergies, and fibrosis." (PMID 39687635, 2024). "By contrast, OVA allergy Tomato+ cells upregulated Th17-associated genes (Il17a, Il22, Rorc, Them176a)." (PMID 37191720, 2023). "By phenotyping animals being protected from food allergy we determined a reduced uptake of OVA, presumably due to a tighter epithelium, elevated allergen-specific IL-22 levels and absence or higher abundance of distinct bacterial strains to be associated with allergy protection." (PMID 27789346, 2016). "Our results show that the reduction in frequency and number of eosinophils and CD11c+CD11b+ cells were accompanied by a reduction in IL-22 concentrations, confirming that IL-22 acts as a pro-inflammatory mediator in the airway allergy inflammation." (PMID 37445595, 2023). "A subpopulation of Th17 lymphocytes mainly produces the cytokines IL-17, IL-21 and IL-22, regulates inflammatory processes and participates in the response directed against microorganisms and in the development of allergic diseases." (PMID 36139446, 2022). "IL-22 attenuates the allergic response in the lungs of mice, demonstrating the negative regulatory function of IL-22 in allergy." (PMID 26565810, 2015). "Further investigation has to show whether IL-17 and IL-22 could be an interesting target for to controlling changes of tissue, in particular in chronic allergic reaction." (PMID 30402605, 2017). "Knowing that IL-22 has frequently been associated with allergic diseases, it is not totally surprising that we found its association with egg- and milk-specific IgE in this study." (PMID 23330224, 2012). "Therefore, the role of IL-22 in allergic diseases is not clearly established." (PMID 33435598, 2021).
inflammatory skin disease (19 papers, 2010 to 2024). Inflammatory skin disorders covers a broad category that includes many conditions ranging in severity, from mild itching to grave medical health complications These disorders are common in people of all ages and races. "Of note, most inflammatory skin disorders are associated with IL-22 and IL-22 blockade is beneficial in these patients." (PMID 35383266, 2022). "MicroRNA-184 has also been shown to increase in response to interleukin-22 (IL-22), a proinflammatory cytokine associated with inflammatory skin disorders, thereby reducing expression of Argonaute-2 (AGO 2) protein in human keratinocytes." (PMID 25612225, 2015). "Emerging findings of regulatory function of IL-17 in the skin raise the possibility of potential negative impacts on skin barrier function, aggravated by the emergence of IL-22 as the pathogenic effector in fulminant skin inflammatory disorders with interference of IL-17R signaling." (PMID 32065580, 2020). "Thus, this study is the first to demonstrate that an increase in IL-22 production and IL-22Rα expression may be associated with inflammatory skin disease." (PMID 28558005, 2017). "Other genes, such as IL-21R, GSDMC, CCR7, TLR9, HAS1/3, IL-17A, IL-22, and CXCL10, have been previously identified as genes associated with various inflammatory skin disorders." (PMID 38612783, 2024). "Additional studies regarding the effect of UVB-induced IL-22 production and IL-22Rα expression on the production of IL-1α, IL-6, and IL-18 will provide a basis for further understanding the role of IL-22 in the control of inflammatory skin disease." (PMID 28558005, 2017). "Natural killer cells, natural killer T cells and a newly identified T helper cell, Th22 cells, which are involved in inflammatory skin disorders, are sources of IL-22." (PMID 21144017, 2010). "Given that IL-1α and IL-6 are involved in the pathogenesis of skin diseases caused by proliferation of keratinocytes, IL-22-dependent regulation of UVB-induced IL-1α, IL-6, and IL-18 production may be important in the mechanism of inflammatory skin diseases." (PMID 28558005, 2017). "Anti-CD1a blockade was able to effectively inhibit recognition of GAS-infected K562-CD1a cells by IL-22-producing polyclonal ex vivo blood T cells, suggesting the possibility of therapeutic intervention in GAS-driven inflammatory skin disease." (PMID 37267382, 2023). "Various reports suggest that IL-22, as opposed to IL-17A, contributes more to the development of chronic lesions and excess type 2 deviations in inflammatory skin diseases derived from SA." (PMID 36076953, 2022). "In patients with inflammatory skin disorders, these TH22 cells were found to produce only IL-22 but not IFNγ, IL-4, or IL-17." (PMID 23460846, 2013). "Genes with a smaller degree of differential expression (e.g., IL22 and IL23) observed in other inflammatory skin diseases may have not passed this FC cut-off, potentially preventing the identification of significant disease related pathways and associations with host response." (PMID 32886659, 2020).
Cirrhosis (18 papers, 2013 to 2025). A chronic disorder of the liver in which liver tissue becomes scarred and is partially replaced by regenerative nodules and fibrotic tissue resulting in loss of liver function. "Multivariate logistic regression identified elevated TBil and reduced CD38 and IL-22 levels were associated with increased cirrhosis risk." (PMID 40417691, 2025). "This study underscores the critical roles of TBil, CD38, and IL-22 in cirrhosis development among AIH patients and validates the diagnostic and prognostic significance of TSP-1, Gal-3, Cys-C, AIb, and PA in compensated cirrhosis." (PMID 40417691, 2025). "Studies have found that in patients with cirrhosis, high serum IL-22 concentration is associated with the occurrence, progression, and mortality of ACLF." (PMID 36117587, 2022). "IL-22 was involved in hepatofibrosis (HF) and cirrhosis associated with HCV infection." (PMID 34434945, 2021). "Multivariate logistic regression analysis identified TBil, CD38, and IL-22 as independent factors influencing cirrhosis development in AIH patients." (PMID 40417691, 2025). "Combined detection of TBil, CD38, and IL-22 levels demonstrated high sensitivity and specificity for predicting cirrhosis development in AIH patients, highlighting their potential as reliable biomarkers for early identification and risk assessment." (PMID 40417691, 2025). "Persistent alterations are observed only in chronic HCV patients with cirrhosis, displaying a distinct long-term pattern compared to IL-10, IL-22, TNFα, IFNγ, and IL-6." (PMID 39578604, 2024). "Interleukin-22 (IL-22) facilitates the development of cirrhosis to HCC through Signal transducer and activator of transcription 3 (STAT3) signal activation." (PMID 38022519, 2023). "HBV-related cirrhosis progression correlated with IL-17A and IL-22 production by ILC3s, suggesting ILC3 promotion of fibrosis, likely in part due to IL-22-mediated suppression of anti-fibrotic IFN-γ." (PMID 35359972, 2022). "However, TBil levels were significantly higher, and CD38 and IL-22 levels were significantly lower in the cirrhosis group." (PMID 40417691, 2025). "We found higher frequencies of IL-22-producing T helper cells in AH patients (median 1.7%) than in cirrhosis patients (1.0%, p = 0.03) and healthy controls (1.0%, p = 0.01), and a 1.5-fold increase in the plasma concentration of IL-17A in AH compared with healthy controls (p<0.01)." (PMID 23372820, 2013). "Taken together, professors suggested that serum IL-22 levels could be a negative prognostic indicator in patients with HBV-related HCC, and that IL-22 should not be used in patients with pre-cancerous cirrhosis or liver cancer." (PMID 24623532, 2014). "The study found that patients with ACLF of IL-22BP/IL-22 ratio is lower than the patients without ACLF, during the period of cirrhosis development for ACLF and eventually death rates of IL-22BP/IL-22 which are declining gradually." (PMID 36117587, 2022).
periodontitis (17 papers, 2017 to 2026). An acute or chronic inflammatory process that affects the tissues that surround and support the teeth. "The researchers observed significantly elevated levels of AHR and interleukin-22 (IL-22) in patients with periodontitis, which were found to be associated with osteoclast resorptive activity and disease severity." (PMID 39575260, 2024). "Another IL involved in periodontitis-associated bone catabolism is IL-22." (PMID 36902030, 2023). "Oral inoculation of bacteria in mice stimulates the production of IL-22 through increased numbers of IL-22-expressing CD4+ T-cells in periodontitis-affected tissues." (PMID 38919613, 2024). "Th22 cells are a subpopulation of T-helper cells that produce IL-22 and TNF, which have been linked to the pathogenesis of periodontitis by increasing inflammation and the number of Th17 cells in periodontal lesions." (PMID 38919613, 2024). "Levels of IL-22 were significantly higher in the gingiva of patients with periodontitis as compared to healthy individuals and were positively correlated with pocket depth." (PMID 36902030, 2023). "In the paper that compared cytokine levels for 54 periodontitis patients and 40 healthy controls, cytokines IL‐1β, IL‐4, IL‐6, IL‐10, IL‐17A, IL‐17F, IL‐21, IL‐22, IL‐23, IL‐25, IL‐31, IL‐33, IFN‐γ, sCD40L and TNF‐α were measured in saliva and serum at baseline, 3, 6 and 12 months after treatment." (PMID 41580300, 2026). "And our data showed that periodontitis microbiota helped the ILC3s to overexpress in the small intestine and spleen and the intestinal IL22 from ILCs, which might be critical to promote inflammatory immune regulation in the progression of T1D." (PMID 35756043, 2022). "Compared to SH, CD4 + T cells were significantly activated by periodontitis microbiota, with the accumulation of IFNγ+ CD4 (p < 0.05), IL17+ CD4 (p < 0.05), and IL22+ CD4 (p < 0.05) T cells in the small intestine." (PMID 35756043, 2022). "High levels of IL-17A, IL-17F IL-22, IL-25, IL-33, IL-10 and INF-y were found in gingival biopsies compared with intestinal biopsies from patients with IBD and periodontitis." (PMID 34501547, 2021). "Consistent with the results in our study, periodontitis microbiota could activate Th1, Th17, and Th22 lymphocytes by increasing the cytokines level of IFNγ, IL17, and IL22 in the small intestine." (PMID 35756043, 2022).